ROR1 (ROR family WNT receptor 1)
Diseases named in the same sentence as ROR1 in open-access papers (continued):
Sharing a sentence is not in itself a finding about the gene and the disease.
tumor (continued). "A phase I clinical study (NCT02706392) from Fred Hutchinson Cancer Research Center was designed to assess the safety and anti-tumor effects of autologous anti-ROR1 CAR-T cells transplanted into patients with advanced, ROR1-positive, stage IV NSCLC." (PMID 33025047, 2021). "These included C-X-C motif chemokine ligand 12 (CXCL12), c-Met, receptor tyrosine kinase-like orphan receptor 1 (ROR1), and fibronectin 1 (FN1), which are associated with activated neoplasia, invasion, migration, and metastasis." (PMID 34069906, 2021). "Treatment of the tumour bearing mice with ROR1-CAR T cells previously exposed to pentanoate led to tumour regression in these animals." (PMID 34658896, 2021). "WNT5a has dual effects on the tumor microenvironment; it can activate the autocrine ROR1/Akt/P65 pathway and promote immune cell inflammation and chemotaxis." (PMID 34565373, 2021). "High expression of ROR1 in breast adenocarcinoma was associated with epithelial-mesenchymal transition (EMT), tumor metastasis, and aggressive disease." (PMID 34123850, 2021). "In these studies, ROR1 inhibition has been shown to synergize with various drug agents for tumor eradication." (PMID 32020017, 2020). "ROR1 was shown to inhibit apoptosis, potentiate EGFR signaling and reported to be overexpressed and associated with poor prognosis in several tumor models." (PMID 33172431, 2020). "Higher concentrations of the ROR1 inhibitor are needed to overcome the apoptotic inhibiting effect of stromal cells to achieve optimal tumor cell killing as also shown for CLL cells." (PMID 32586008, 2020). "For the matched normal and tumour tissues (n = 19), the expression level of ROR1 or ROR2 was significantly different between tumour and adjacent normal tissues." (PMID 32807831, 2020). "ROR1 is an oncofetal tyrosine kinase highly expressed in several neoplasms but minimally expressed in normal adult tissue making it an appealing candidate for targeted therapies." (PMID 32020017, 2020). "In the endometrioid EC patients, the expression level of ROR1 was significantly correlated with tumour grade (p = 0.019)." (PMID 32807831, 2020). "Silencing ROR1 or ROR2 in different tumour types has been shown to inhibit proliferation and decrease metastatic potential." (PMID 32807831, 2020). "Not only was ROR1 functionally relevant to EC tumorigenesis and progression, ROR1 expression was found to be significantly increased in EC tumour tissue compared to normal tissue." (PMID 32807831, 2020). "We first measured the therapeutic efficacy of systemically injecting tumor-bearing mice with 106 ex vivo-transduced CAR+ T cells specific for the tumor antigen ROR1." (PMID 33247092, 2020). "Tumor-associated ROR1 is a candidate target for CAR-T, but CAR-T against ROR1 induces lethal bone marrow failure due to recognition of ROR1+ stromal cells." (PMID 32185403, 2020). "The specific expression of ROR1 by tumor cells and its absence in normal tissues makes of this receptor an ideal theoretical target for cancer treatment." (PMID 33172431, 2020). "Nevertheless, protection from toxicity was provided only when the ROR1-positive tumour cells where spatially separated from ROR1-positive normal cells as toxicities where observed when tumour cells and normal cells were co-localized." (PMID 32824734, 2020). "In the present study, ROR1 expression was evaluated in tumor material from DLBCL patients with different clinical presentation and outcome." (PMID 32586008, 2020). "In conclusion, the expression of the receptor tyrosine kinase ROR1 is associated with a poor prognosis in several malignancies including DLBCL and of importance for tumor cell proliferation survival, metabolism and epithelial-mesenchymal-transition (EMT)." (PMID 32586008, 2020). "ROR1 is overexpressed in chemoresistant BC where it correlates with poor therapy response and tumor recurrence." (PMID 32020017, 2020).
tumor (continued). "Because ROR1 is enriched in cancer stem cell populations, ROR1 inhibition would also repress cancer stemness, a key feature of recurrent and chemoresistant neoplasms." (PMID 32020017, 2020). "The high expression of ROR1 in tumor cells is known to contribute to an enhanced rate of cell survival, proliferation, migration and chemotaxis." (PMID 31382410, 2019). "Recently, strong evidence has associated ROR1 expression with cancer stem cells (CSCs), epithelial–mesenchymal transition (EMT) and chemoresistance, making this receptor a critical factor in tumor metastasis and recurrence." (PMID 31382410, 2019). "A potent immunotherapeutic approach was used to develop bispecific antibodies (biAbs) that combine a T cell-engaging arm with a tumor cell-binding arm, for which ROR1 seemed a perfect candidate due to its relatively restricted expression on tumor cells." (PMID 31382410, 2019). "ROR RTKs have always been deemed to be tumor promoters, especially ROR1, which has been reported to be involved in tumor progression in multiple cancers." (PMID 31878941, 2019). "In order to generate a consistent ROR1+ tumor model in huNSG mice, we have to improve the transduction efficiency of CD34+ cells and achieve a higher engraftment of TCL-1-transduced CD34+ cells." (PMID 29850623, 2018). "A significant association between the expression of ROR1 and activated AKT/CREB enhancing tumor cell growth has also been reported." (PMID 29856777, 2018). "It blocks ROR-dependent non canonical Wnt5a signaling through ROR-1 dephosphorylation, thus blocking tumor cell proliferation, migration and survival, leading to tumor cell death by apoptosis." (PMID 29387053, 2017). "Our study confirms previous findings that ROR1 is expressed on some normal tissues, which raises the possibility of on-target off-tumor toxicities." (PMID 28811962, 2017). "Engineered T cells expressing a ROR1-specific CAR can recognize the tumor cells and exhibit significant anti-tumor effects in B-CLL." (PMID 28427197, 2017). "We first assessed the effect of ROR1-cFab on the regulation of tumor cell viability using the CCK8 assay." (PMID 29212222, 2017). "In a preclinical study, Cirmtuzumab (UC-961), a first-in-class humanized mAb against ROR1, exerted a good anti-tumor effect in CLL." (PMID 28427197, 2017). "In summary, we provide the first systemic evaluation and proof of concept of an ROR1 BiTE and show T-cell-mediated efficacy against a panel of solid tumors, raising the prospects of targeting a range of tumor types." (PMID 28811962, 2017). "Functional assays revealed that ROR1-cFab inhibited tumor cell proliferation and migration, as well as inducing apoptosis of ROR1-positive A2780 cells in a dose dependent manner." (PMID 29212222, 2017). "Variation in ROR1 expression between tumor types, as well as within cells lines derived from tumors of the same histological origin, was observed." (PMID 28811962, 2017). "The staining results showed that ROR1, which was predominately located on the membrane of tumour cells, was strongly expressed in 13 of 60 (21.7%) paraffin-embedded NPC specimens." (PMID 28687750, 2017). "When normalized to the total loading proteins, ROR1 expression in lung ADC samples was statistically much higher than that in the matched non-tumor tissues (P < 0.001)." (PMID 27830754, 2016). "The results revealed that ROR1 protein expression was significantly higher in lung ADC tissues than that in their adjacent non-tumor tissues." (PMID 27830754, 2016). "Treating primary ovarian patient-derived xenograft (PDX) tumor cells, which express high levels of Ror1 with an anti-Ror1 mAb (UC-961) inhibited spheroid formation and migration in vitro and engraftment in immune-deficient mice." (PMID 27571105, 2016). "Before constructing CARs from 4A5, a mAb with specificity for human ROR1, we sought to validate its staining of tumor cells." (PMID 26030772, 2015).
tumor (continued). "Clinical trials will investigate the ability of ROR1-specific CAR+ T cells to specifically eliminate tumor cells while maintaining normal B-cell repertoire." (PMID 26030772, 2015). "We show that T cells expressing either CAR can proliferate in response to cells bearing ROR1 and specifically kill ROR1+ tumor cells." (PMID 26030772, 2015). "The results showed that the expression of ROR1 protein was either high or low in tumor cells, while the ROR1 protein in normal mucosal cells was rarely expressed." (PMID 26576539, 2015). "We demonstrate that SB transposition achieved stable CAR expression in T cells and, in concert with co-culture on clone#1 AaPC, resulted in heterogeneous outgrowth of T-cell memory populations with ROR1-restricted anti-tumor activity." (PMID 26030772, 2015). "In summary, ROR1-specific CAR+ T cells demonstrated effective in vitro specific lysis of ROR1+ tumor cells in both autologous and allogeneic settings." (PMID 26030772, 2015). "It was shown that the upregulation of ROR1 was significant in the GC tissues compared to the paired adjacent non-tumor samples." (PMID 26576539, 2015). "Within non-small cell lung cancer cells, silencing of ROR1 disrupts the ability to escape anoikis, anchorage-dependent programmed cell death, and decreased primary tumor growth when the cells are transplanted into nude mice." (PMID 24752542, 2014). "Further research is required to elucidate the tumor-specific mechanisms of ROR1 overexpression and the contribution of ROR1 to initiation and progression of cancer." (PMID 24752542, 2014). "Further studies are needed to understand the mechanisms of ROR1 phosphorylation which seems to be of importance for the malignant phenotype of many tumor cells." (PMID 24205204, 2013). "Because Ror1 is an orphan receptor about which little is known, we first examined the expression pattern of endogenous Ror1 in various human tumor cell lines of different tissue origins." (PMID 20587074, 2010). "Constitutive Stat3 phosphorylation has been found in several solid tumors and hematologic malignancies, and it is likely that ROR1 will be detected in these neoplasms as well." (PMID 20686606, 2010). "Notably, ROR1 is highly expressed in various tumor cell types but exhibits minimal expression in healthy adult tissues, providing a strong basis for therapeutic exploitation." (PMID 39849645, 2025). "Notably, targeting ROR1 can effectively reduce tumor growth, making it an attractive candidate for CAR-T cell therapy." (PMID 39849645, 2025). "The ROR1-reactive HTLs effectively induced direct cytotoxicity against HLA-DR-matched tumor cells." (PMID 40723210, 2025). "In addition, our short-term T-cell activation protocol using the ROR1 peptide effectively identified tumor-reactive T-cells in PBMCs." (PMID 40723210, 2025). "First, poorly differentiated and undifferentiated tumours show higher ROR1 expression." (PMID 41355329, 2025). "All primary tumours from patients with skin metastases showed low ROR1 expression (6 cases)." (PMID 41355329, 2025). "Furthermore, the residual macrophages were observed rather in the middle of the tumor, whereas a higher cell death was seen near the rim area, where also the ROR1 expression was strongest, in accordance with ROR1 being involved in cell migration and invasion." (PMID 41479906, 2025). "ROR1 kinase is an underexplored promising target for the development of novel anticancer drugs, being strongly expressed in several cancer cell lines, but poorly in non‐tumor cells." (PMID 40328670, 2025). "Since ROR1 expression is connected to poorly differentiated tumours and tumours with lymphatic metastasis formation, it may be used as a diagnostic marker to evaluate the aggressiveness of the tumour." (PMID 41355329, 2025). "In addition, ROR1-targeting CAR-T cells were developed to assess cytotoxic activity against ROR1+ tumor cells, and the effect of cytokine stimulation on their efficacy was evaluated." (PMID 39849645, 2025).
tumor (continued). "Hence, in hematologic malignancies, the inhibition of ROR1 is sufficient to attenuate tumor growth, stressing the importance of understanding ROR1′s role in mediating treatment resistance." (PMID 40869147, 2025). "Furthermore, understanding how ROR1 expression is modulated by the tumor microenvironment, such as immune infiltration, hypoxia, or mesenchymal stromal cells will be vital." (PMID 40869147, 2025). "Consequently, ROR-1 has been identified as a potential target for tumor-directed therapeutic interventions." (PMID 41477115, 2025). "Next, we investigated whether ROR1-reactive HTLs exhibit antitumor activity against ROR1-expressing tumor cell lines." (PMID 40723210, 2025). "This limited expression pattern suggests that CD155 may have a lower risk of on-target, off-tumor effects when compared with EGFR, ERBB2, and ROR1." (PMID 40478751, 2025). "In addition, ROR1-reactive HTLs produce granzyme B, which directly induces tumor cell death, as confirmed by their cytotoxicity against ROR1+ HNSCC cell lines." (PMID 40723210, 2025). "There are several tumor suppressors other than CREB3L1 that could be silenced by ROR1, suggesting that targeting ROR1 and its downstream DNMT-mediated epigenetic modifications could provide a novel therapeutic strategy for TNBC." (PMID 40427627, 2025). "Prospectively selecting participants or tumor subtypes for ROR1 expression could result in higher antitumor activity." (PMID 40762544, 2025). "Additionally, across several tumor types, it has been reported that ROR1 signals with YAP/TAZ to regulate EMT and stemness markers like BMI-1, indicating a common crosstalk between signaling pathways across diverse cancer types." (PMID 40869147, 2025). "Additionally, immune pressure exerted by vaccination can lead to downregulation of ROR1 expression in tumor cells, facilitating immune evasion." (PMID 40723210, 2025). "In this study, perineural invasion was associated with significantly higher expression of ROR1 compared to tumour samples without perineural invasion." (PMID 41355329, 2025). "Furthermore, due to its long half-life and tumor-targeting properties, ROR1 DAC exhibited superior in vivo antitumor activity and a safety profile." (PMID 39816690, 2025). "For functional validation, ROR1-positive tumor cells were selected." (PMID 39849645, 2025). "This immunosuppressive TME poses challenges for effective cancer therapies, including the use of chimeric antigen receptor (CAR) T cells to significantly inhibit tumor growth and improve survival by targeting tumor-associated antigens like EpCAM, EGFR, and ROR1." (PMID 41375062, 2025). "For example, extensive tumor metastases in bone marrow (BM) could activate ROR1 CAR expression and lead to the elimination of normal ROR1+ BM stromal cells." (PMID 40308611, 2025). "We hypothesized that intratumoral delivery of IL-21 by C021 would amplify the local anti-tumor efficacy of anti-ROR1-CAR-NK cells against NB." (PMID 39895691, 2025). "Receptor tyrosine kinase-like orphan receptor 1 (ROR1) is a member of the type I receptor tyrosine kinase (RTK) family that shows low or minimal expression in healthy (adult) tissues whereas is highly expressed in various tumor cell types." (PMID 41339932, 2025). "ROR1 targeting would likely be the most effective in co-treatment regimens by first inhibiting the CSCs to reduce drug resistance and metastasis, then following with debulking surgery and chemotherapies to eliminate the rest of the tumor." (PMID 40869147, 2025). "By targeting ROR1, tumor cell growth could be inhibited as ROR1 possesses properties typical of a tumor-associated antigen, and multiple studies reported a relationship between ROR1 and human cancer cells." (PMID 39551787, 2024).
tumor (continued). "They designed ROR1-directed CAR-T cells to co-express EpCAM or B7-H3-specific synthetic notch receptors which functioned as a logic gate to restrict CAR-T cell activity to tumor cells that expressed the ligands for the synthetic notch receptors." (PMID 39796666, 2024). "Moreover, the prominent ROR1 membrane pattern observed in tumour cells, which should reflect v1 protein expression, has supported the development of an extensive variety of new immune-based treatments." (PMID 39495778, 2024). "Considering the limited amount of data published on haematological indications investigating morphologically intact tumours from lymph nodes or bone marrow, we performed this prevalence with a well characterized anti-ROR1 clone 6D4 for IHC, using commercially available FFPE tissue samples." (PMID 39495778, 2024). "This highly positive ROR1 membrane profile in CLL and HCL could help to avoid patient selection for trial recruitment in case ROR1 is used as tumour target for ADC, TCE, or CAR-T development." (PMID 39495778, 2024). "Inhibiting ROR1 activity could also potentially disrupt the signaling pathways involved in cancer development and progression, leading to a reduction in tumor growth and an improved response to therapy." (PMID 39551787, 2024). "In a mouse model of ROR1-positive NSCLC, after pretreatment with oxaliplatin/cyclophosphamide (Ox/Cy), CAR-T cells showed better penetration of the tumor tissue, resulting in increased chemokine release from tumor-associated macrophages." (PMID 38919533, 2024). "Our findings demonstrate that inhibition of the lncRNA DLEU2/ROR1 pathway may complement the antitumor or anti-metastatic activity by eliminating drug-resistant CSCs or inhibiting tumor cells from acquiring CSC-like characteristics." (PMID 38296962, 2024). "This strategy resulted in tumor regression in ROR1 + tumor cells with reduced toxicity." (PMID 38622705, 2024). "Therefore, a more refined tumour membrane assessment, specific to v1 expression, will require a v1 specific anti-ROR1 Ab." (PMID 39495778, 2024). "Interestingly, high expression of ROR1, ROR2, and FZD2 were associated with a higher proportion of T cell‐inflamed tumor." (PMID 38558536, 2024). "However, at least partially due to the lack of available commercial reagents, few studies have been conducted regarding the prevalence of ROR1 expression across tumor types." (PMID 38791952, 2024). "Although numerous antigens have been identified as potential targets (e.g., Trop2, GD2, ROR1, MUC1, EpCAM), the ideal target should represent the most relevant obstacle, thereby minimizing on-target/off-tumor toxicities and reducing tumor escape via antigen loss and intrinsic heterogeneity." (PMID 39062758, 2024). "Inhibition of ROR1-signaling enhances the anti-tumor activity of paclitaxel in preclinical models." (PMID 38408999, 2024). "However, in cancer, ROR1 is reactivated, which stimulates tumor cell growth, differentiation, and proliferation through the WNT/ROR1 pathway." (PMID 39551787, 2024). "All four constructs showed comparable T cell-mediated killing of ROR1+ tumor cells." (PMID 38455046, 2024). "The number of ROR1 molecules present in the cell membrane per tumour cell, as well as the minimum amount of ROR1 positive tumour cells per cancer lesion required to secure therapeutic success are relevant aspects that cannot be addressed by this kind of prevalence analysis." (PMID 39495778, 2024). "In humans, ROR1 exhibits low expression levels in the parathyroid glands, pancreatic islets, adipose tissue, lungs, and gastrointestinal tract, but its expression is increased in tumor cells." (PMID 39551787, 2024).